RAB27B (RAB27B, member RAS oncogene family)
Diseases named in the same sentence as RAB27B in open-access papers (continued):
Sharing a sentence is not in itself a finding about the gene and the disease.
tumor (continued). "CD31 immunostaining was significantly decreased by approximately 40% in shRAB27B tumors compared with shNT tumors, indicating that RAB27B in the CSCs is important for tumor angiogenesis." (PMID 37077938, 2023). "Regarding tumor grade, higher RAB27B expression was observed in grade III tumors, compared to grade I and grade II tumors (p = 0.023)." (PMID 36980570, 2023). "Rab27 has been shown to control the exosome secretion pathway, and knockdown of either Rab27a or Rab27b inhibits this pathway in the tumor cell line HeLa B6H4." (PMID 34483204, 2021). "The roles and molecular mechanisms of Rab27b in mediating radioresistance and tumor growth after irradiation should be investigated in more detail in future studies." (PMID 33409495, 2020). "Knockdown of Rab27b in U87MG cells combined with radiation treatment suppressed orthotopic tumor growth in the mouse brain and prolonged the survival of recipient mice." (PMID 33409495, 2020). "While the function of Rab27A and Rab27B in exosome release has been established in a number of models, Rab27A has additional exosome-independent roles in tumor progression." (PMID 30925917, 2019). "GTPases Rab27b can regulate exosome release in some tumor cells, and this was demonstrated to be a therapeutic target (using RNAi) for reducing tumor progression." (PMID 30941051, 2019). "Especially, the small GTPases, RAB27A and RAB27B, were participated in exosome secretion in various human tumor cells." (PMID 31402975, 2019). "Rab GTPases, including Rab27a and Rab27b, are the key regulators of exosomes secretion and Rab27 is closely related to the occurrence and the development of tumor, which indicates the role of exosomes secretion in tumor biology." (PMID 30217217, 2018). "Recent reports have indicated the involvement of Rab27A and Rab27B in promoting cell invasion and tumor metastasis." (PMID 30081925, 2018). "Immunohistochemical analysis of Rab27B, mesenchymal markers, and epithelial markers was performed in 221 tumor specimens from patients with invasive breast cancer." (PMID 30081925, 2018). "For example, Rab2A, Rab3D, Rab8, Rab11, Rab21, Rab22A, Rab23, Rab25, Rab27B, and Rab35 promote tumor cell migration, invasion and metastasis by disrupting the homeostasis of intracellular signal transduction and vesicles trafficking." (PMID 30158579, 2018). "The results revealed that downregulated expression of RAB27B in BEL7402 cells significantly lead to diminished tumor sizes than those in the SCR group." (PMID 28977851, 2017). "The siR plasmid was used to knockdown the expression of RAB27B to further determine its biological role in tumor cell proliferation and cell cycle." (PMID 28977851, 2017). "An increased expression of Rab27B is associated with the poor prognosis of oestrogen receptor-positive breast cancer patients, supporting the role of Rab27B in tumor promotion." (PMID 27716280, 2016). "The results indicated that high Rab27b expression (P = 0.041) and tumor differentiation (P = 0.001) are two independent prognostic factors for CRC." (PMID 25580113, 2014). "In this study, we demonstrated high Rab27b expression in CRC tissues and demonstrated that CRC patients with elevated Rab27b expression are prone to encounter tumor metastasis and unfavorable prognosis." (PMID 25580113, 2014). "Total RNA was extracted from 18 CRC tissues and matched tumor-adjacent tissues and subsequently subjected to one-step qPCR for the evaluation of the expression of Rab27b mRNA." (PMID 25580113, 2014). "Kaplan-Meier survival curves indicated that CRC patients with high Rab27b expression and poor tumor differentiation suffered a significantly shorter survival time." (PMID 25580113, 2014). "In tumor cells, high Rab27B protein expression with nuclear staining was detected in 88 of 162 (54.32%) GIST tissues and the remaining 74 showed low or no Rab27B protein expression with nuclear staining." (PMID 25382899, 2014).
tumor (continued). "RAB27B regulates invasive tumour growth and metastasis in ER-positive breast cancer cell lines and xenograft murine models." (PMID 24931391, 2014). "High nuclear staining of Rab27B was significantly associated with tumor size (P = 0.006), mitotic index (P = 0.013), AFIP Miettinen risk classification (P = 0.002), and tumor grade (P = 0.021)." (PMID 25382899, 2014). "Overexpression of Rab27B in non-invasive ER-positive breast cancer cells comparable to levels found in poor-prognosis primary breast tumors, stimulated invasive tumor growth." (PMID 21304180, 2010). "It was also found that the loss of adipose tissue in LLC tumor-bearing mice could be attenuated by the administration of omeprazole, an inhibitor of HSP70 and HSP90 positive EVs release by blocking Rab27b synthesis in tumor cells." (PMID 39697630, 2024). "Mechanistically, our results suggest that RAB27B fuels tumor cell proliferation and angiogenesis." (PMID 37077938, 2023). "To determine whether these observations recapitulate in primary human NSCLC cells, we next analyzed RAB27B mRNA abundance in stem-like cultures established from primary human NSCLCs obtained from patients undergoing tumor resection." (PMID 37077938, 2023). "Previous studies have shown that RAB27B could regulate cell signal transduction and exosome release, and thus influence tumor proliferation and drug resistance." (PMID 37692484, 2023). "However, Rab27a and Rab27b have sometimes been reported to act as tumor suppressors, because they are downregulated in colorectal and prostate cancers and their lower levels of expression are correlated with worse outcomes." (PMID 34483204, 2021). "Rab27b knockdown alone was effective at delaying tumor growth and prolonging the survival of mice." (PMID 33409495, 2020). "Moreover, anti-tumor effects of RAB27B downregulation were also observed in sunitinib-resistant RCC cells." (PMID 32379831, 2020). "Since exosome secretion has been reported to increase in environments that are not suitable for cell survival, including chemotherapeutic treatment, hypoxia, heat stress, etc., it is possible that the tumor-suppressive effects of si-RAB27B acted to promote exosome secretion." (PMID 32379831, 2020). "In addition, Rab27A and Rab27B, the family members of Rab37, mediate exosomal pathways discarding tumor-suppressor microRNAs to enhance cancer progression." (PMID 30158579, 2018). "Both Rab27A and Rab27B enhance cell proliferation and tumor development." (PMID 30081925, 2018). "Furthermore, the influence of miR-20a-5p and Rab27B on the growth of tumor xenografts was also addressed in nude mice." (PMID 28265202, 2017). "The suggested mechanism by which Rab27b stimulates invasive tumor growth includes regulation of the heat shock HSP90α protein and the indirect induction of MMP-2, a protease that requires an association with extracellular HSP90α for its activity to accelerate the degradation of extracellular matrix." (PMID 29284484, 2017). "Rab27b also has been shown to promote invasive tumor growth in mouse xenograph models." (PMID 25798887, 2015). "Rab27B-positive staining was mainly localized to the nucleus of the tumor cells." (PMID 25382899, 2014). "Univariate analyses showed that increased nuclear expression of Rab27B (P = 0.009), tumor diameter (P = 0.010), mitotic index (P < 0.001), AFIP Miettinen risk classification (P = 0.049), and tumor grade (P < 0.001) were associated with prognosis of GIST patients for 5-year OS rates." (PMID 25382899, 2014). "We here analyzed the roles of Rab27a and Rab27b in mouse tumor cells." (PMID 26082068, 2012). "Similarly, RAB27B expression was associated with N status, with expression being gradually decreased from N0 status (without lymph nodes infiltration) to N2 status (tumor infiltration in more than 4 regional lymph nodes) (p = 0.022)." (PMID 36980570, 2023).
tumor (continued). "This statement is supported by the fact that alteration of the expression of Rab27a and Rab27b proteins, involved in the transport of late endosomal/lysosomal-like compartments to the plasma membrane in the exosomal pathway, result in an alteration of the tumor-cell-derived exosomes tumoral effect." (PMID 36986603, 2023). "It is well acknowledged that Rab27b is responsible for several secretory mechanisms and many studies have demonstrated that tumor cells use exosomes to communicate with surrounding tissues and immune cells, developing and maintaining an immunosuppressive microenvironment for tumor progression." (PMID 25580113, 2014). "The hot genes with the most positive signal events in the normal-specific group were RBPJ, PFKFB3, CAMK1D, ACACB, and WWOX, whereas the hot genes in the tumor-specific group were SLC35F3, PCDH7, NF1, and RAB27B." (PMID 36895481, 2023). "RAB27A, RAB27B, and RAB35 are abnormally expressed in tumors and participate in the regulation of tumor exosome secretion." (PMID 34088337, 2021). "Along with high levels of methylation of PRMT4, PRMT5, PRMT7, and hnRNPA1 in tumor samples, changes in gene alternative splicing were observed, such as those for PPARA, SREBF2, RAB27B, and WDPCP in BRCA, CRC, and PC samples." (PMID 33782401, 2021). "Silencing of Rab27b decreased GBM cell survival after IR treatment in vitro and further delayed tumor growth and increased overall survival after radiation treatment in an in vivo model." (PMID 33409495, 2020). "When normalized to GAPDH, the means of Rab27b mRNA expression in CRC tissues and the corresponding tumor-adjacent tissues were 4.01 ± 0.301 and 1.50 ± 0.156, respectively (t = 7.429, P < 0.001)." (PMID 25580113, 2014). "We found that the transcript level of Rab27b but not Rab27a was increased in tumor tissues compared with adjacent normal tissues, whereas the protein levels of both Rab27a and Rab27b were increased in tumor tissues." (PMID 40360476, 2025). "In addition, high tumor expression of RAB27A, RAB27B, RAB9A, RAB11B, and STX1A was favorable of a 5-year survival (p = 0.038, p = 0.015, p = 0.008, p = 0.002, and p = 0.028, respectively)." (PMID 36980570, 2023). "Sytl1, a Rab27b partner in hematopoietic cells, facilitates CXCR4 membrane trafficking and promotes occupancy of the bone marrow niche by AML, indicating the importance of the Rab27/Sytl axis in the interaction between tumor cells and the microenvironment." (PMID 37029109, 2023). "Our results show that RAB27B is overexpressed in CSC-enriched cultures from a panel of NSCLC cell lines and is required for enhanced transformed growth, clonal expansion, and invasion in vitro, and for tumor growth in vivo." (PMID 37077938, 2023). "One of the most interesting findings of this study was that mRNA expression of RAB27B was lower in tumor tissues compared to tumor adjacent non-malignant tissues." (PMID 36980570, 2023). "Expectedly, knock-down of Rab27a and Rab27b potently inhibited exosome release from tumor cells without remarkably changing viabilities of the tumor cells." (PMID 34229732, 2021). "Thus, the secretion of soluble factors through the Rab27b pathway after radiation potentially alters cancer cell subtypes and/or induces transdifferentiation in the GBM tumor microenvironment." (PMID 33409495, 2020). "In addition, Rab27b regulates EREG in response to the IR treatment, and EREG interacts with adjacent cells to promote tumor progression." (PMID 33409495, 2020). "To test the hypothesis that tumor released exosomes induce tumor innervation, we utilized CRISPR/Cas9 to genetically modify Rab27A and Rab27B in mEERL parental cells." (PMID 30327461, 2018). "Negative expression of Rab27b significantly correlated with tumor differentiation and positive vascular invasion." (PMID 30627227, 2018). "Moreover, expression of RAB27B was upregulated in HCC tissues, and correlated with tumor progression and poor prognosis." (PMID 28977851, 2017).
tumor (continued). "We found two deleted regions shared by both tumor types in three out of the four cell lines H23R, A2780R, and OVCAR3R, but not in H460 cells, located on 18q21.2–18q21.31 and 18q21.32, affecting the genes RAB27B, CCDC68, TCF4, TXNL1, WDR7, and BOD1P; and genes ZNF532, SEC11C, GRP, respectively." (PMID 32224864, 2020). "Indeed, immunohistochemistry in TUR specimens showed that patients with AR-positive or Rab27b-positive non-muscle-invasive bladder tumor subsequently undergoing BCG therapy had a significantly higher risk of postoperative disease recurrence, compared to those with AR/Rab27b-negative tumor." (PMID 40486871, 2025). "Our study shows that RAB27A, RAB27B, RAB2B, and RAB3B mRNA levels were lower in tumor tissues compared to tumor adjacent, non-malignant tissues (p < 0.001, p = 0.009, p = 0.011, and p < 0.001, respectively)." (PMID 36980570, 2023). "Microarray profiles comparing GSLCs and non-stem tumor cells (NSTCs) isolated from primary human GBM (GBM-1) showed that 4 out of 100 members in the Ras-superfamily (RAB26, RAB27B, RAB6B and ARL4C) were significantly up-regulated in GSLCs (P < 0.05)." (PMID 33403039, 2021). "High Rab27b expression was detected in 49 (43.4%) out of 113 CRC tissues and in 23 (20.4%) out of tumor-adjacent noncancerous tissues." (PMID 25580113, 2014). "Interestingly, RAB27A, RAB27B, RAB2B, RAB3B mRNA levels were lower in tumor tissues compared to tumor adjacent, non-malignant tissues (p < 0.001, p = 0.009, p = 0.011 and p < 0.001, respectively)." (PMID 36980570, 2023).
cancer (37 papers, 2012 to 2024). A tumor composed of atypical neoplastic, often pleomorphic cells that invade other tissues. "Further exploration will reveal the detailed mechanisms underlying the role of RAB27B in RAS-driven cancers and the therapeutic potential of targeting RAB27B in the treatment of hematopoietic malignancies." (PMID 37317974, 2023). "RAB27B protein expression has been reported to associate with progression of a variety of human cancers including ovarian, liver, colorectal, breast and the two major forms of NSCLC, LUAD, and LUSC." (PMID 37077938, 2023). "Rab27b is reported to associate with the development and progression of several types of human cancers." (PMID 30627227, 2018). "Recently, mounting evidence has reported that elevated expression of Rab27b could be observed in various kinds of cancers and is highly associated with malignant behaviors." (PMID 30627227, 2018). "In addition, it is reported that aberrant expression of Rab27B is associated with several types of cancers." (PMID 28265202, 2017). "Our findings reveal the critical roles of TGF‐β and RAB27B in cancer development by regulating EV release and composition and thus provide potential targets to improve cancer immunotherapy." (PMID 39723610, 2024). "For example, components of the ESCRT complexes, SNARE proteins, syntenin, heparanase and small Rab GTPases (such as RAB27B) are overexpressed in various cancers including NSCLC." (PMID 38765006, 2024). "Nonetheless, RAB27B silencing decreased cancer stemness in each CSC function investigated in our study." (PMID 37077938, 2023). "RAB27B is reported to be necessary for EV-mediated communication between cancer cells, which contributes to cancer progression and metastasis." (PMID 37077938, 2023). "In order to determine which is the best Rab GTPase to analyze as a surrogate marker for secretion of exosomes by cancer cells, we screened for four Rab GTPases (Rab5, Rab7, Rab27a and Rab27b) using three human PDAC cell lines (PANC-1, BxPC-3 and MIA PaCa-2)." (PMID 37641131, 2023). "RAB27B, a member of the Rab group, has been widely shown to play a crucial role in facilitating cancer progression and metastasis." (PMID 35164665, 2022). "Since cancer cell lines overexpressed two subtypes of Rab proteins (Rab27a and Rab27b) involved in the process of exosome release, cancer cells are also considered as efficient exosome producers." (PMID 34503245, 2021). "As well as our demonstration, the oncogenic effects of RAB27B have been reported in several types of cancer." (PMID 32379831, 2020). "RAB27B is one of the leading proteins involved in exosome secretion, and oncogenic effects have been reported in several cancers." (PMID 32379831, 2020). "All studies performed immunohistochemistry to evaluate Rab27A or Rab27B expression in the human cancer tissue, and the majority of the cut-off value were scoring system using staining intensity and proportion." (PMID 32839520, 2020). "Knockdown of Rab27A or Rab27B reduces exosome release in different cancer cell types, including bladder cancer cells, cervical cancer cells, breast cancer cells, melanoma cells, and lung adenocarcinoma cells." (PMID 31438991, 2019). "Both Rab27A and Rab27B have been reported to promote the proliferation, enhance the invasion, and increase the chemo-resistance of cancer." (PMID 31438991, 2019). "As a member of the secretory Rab27 subfamily, Rab27b showed rare expression in normal tissues while it showed high expression in several types of human cancers." (PMID 30627227, 2018). "Anti-HSP90α antibodies reverse the increase in cell proliferation rate and cyclin A expression in Rab27B-overexpressing cells, suggesting that Rab27B promotes cancer growth by inducing exosomal secretion of HSP90α." (PMID 30081925, 2018). "Both Rab27A and Rab27B have been reported to promote cell proliferation, enhance cell invasion, and increase chemoresistance of cancer." (PMID 30081925, 2018).